HMGB1 (high mobility group box 1)
Diseases named in the same sentence as HMGB1 in open-access papers (continued):
Sharing a sentence is not in itself a finding about the gene and the disease.
diabetic retinopathy (continued). "Our findings indicate that retinal pericyte and endothelial injury and death in diabetic retinopathy may be due to HMGB-1-induced cytotoxic activity of glial cells as well as the direct effect of HMGB-1 on endothelial cells." (PMID 24498140, 2014). "Our findings indicate that retinal pericyte and endothelial injury and death in diabetic retinopathy might be due to HMGB-1/PLA2 induced cytotoxic activity of glial cells as well as the direct effect of HMGB-1 on endothelial cells." (PMID 25292258, 2014). "Thus, this study provides further insight into the research on drug target or therapeutic role of HMGB-1/PLA2 in diabetic retinopathy." (PMID 25292258, 2014). "Collectively, our present data suggest that blocking HMGB1 signaling pathways might be a novel therapeutic strategy for neuronal dysfunction in vision-threatening diabetic retinopathy." (PMID 23766563, 2013). "Blocking HMGB1, ROS, or the JNK pathway may attenuate VEGF-A production, suggesting HMGB1 and related signaling molecules play a role in diabetic retinopathy." (PMID 22511847, 2012). "Thus, this study provides further insight into the role of HMGB-1 in diabetic retina and may provide therapeutic opportunities for patients suffering from diabetic retinopathy." (PMID 24498140, 2014). "Therefore, GA and other agents targeted to HMGB1 may provide novel therapeutic options for diabetic retinopathy." (PMID 24733965, 2014). "Thus, our data suggest that retinal pericyte and endothelial injury and death in diabetic retinopathy may be due to HMGB-1-induced cytotoxic activity of glial cells as well as the direct effect of HMGB-1 on endothelial cells." (PMID 24498140, 2014). "The findings from a single cell line study may not be sufficient to explain the pathophysiology of diabetic retinopathy involving the entire retina; however, we believe our results provide the framework for future studies investigating the role of HMGB1 in diabetic retinopathy." (PMID 22511847, 2012). "Our data suggest that HMGB-1 and PLA2 involved in retinal pericyte and endothelial injury and cell death in diabetic retinopathy." (PMID 25292258, 2014). "Based on the previous reports, our present study is aimed to reveal the possible mechanism of HMGB-1 and PLA2 on their involvement in diabetic retinopathy." (PMID 25292258, 2014). "In line with the findings, a recent study demonstrated that HMGB-1 promoted lymphangiogenesis via TLR4/NF-ΚB/MMP9 signaling pathway, indicating that HMGB-1 may play an important role in diabetic retinopathy by modulating MMP9." (PMID 27847406, 2016). "Extracellular HMGB1 functions as a pro-inflammatory cytokine that interacts via receptor for advanced glycation end products (RAGE), and the downstream signaling pathways of RAGE play key roles in the cellular response to diabetic retinopathy." (PMID 26950148, 2016). "From this study, we suggest that HMGB-1 and PLA2 may be interesting targets in managing diabetic retinopathy." (PMID 25292258, 2014). "Interesting reports on the role of inflammatory/proangiogenic high mobility group 1 (HMGB-1) cytokine and phospholipases A2 (PLA2) in neovascularization have diverted our concentration to reveal whether HMGB-1 and PLA2 plays role in diabetic retinopathy." (PMID 25292258, 2014).
multiple sclerosis (23 papers, 2014 to 2025). A progressive autoimmune disorder affecting the central nervous system resulting in demyelination. "HMGB-1 acts as an alarmin that induces tissue deterioration through senescence-associated inflammation, and elevated levels of this protein have been reported in patients with multiple sclerosis and Alzheimer’s disease." (PMID 38965360, 2024). "Taken together, these data demonstrate a potentially important extracellular role for HMGB1 as a factor involved in impaired remyelination in the multiple sclerosis brain." (PMID 35573828, 2022). "In recent years, HMGB1 has brought much interest for its pro-inflammatory role in diseases related to spinal cord injury, such as multiple sclerosis (MS) and related animal models-experimental autoimmune encephalomyelitis (EAE)." (PMID 33868221, 2021). "The inflammatory mediator high-mobility group box 1 (HMGB1) plays a critical role in the pathogenesis of human multiple sclerosis (MS) and mouse experimental autoimmune encephalomyelitis (EAE)." (PMID 30013568, 2018). "The initiation of a pro-inflammatory loop by HMGB1 has been suggested in several models of pathological inflammation as multiple sclerosis, necrosis and preterm birth." (PMID 29149067, 2017). "High mobility group box protein 1 (HMGB1) is a transcriptional regulator that is receiving increasing attention in autoimmune disorders including multiple sclerosis (MS)." (PMID 25879961, 2015). "In multiple sclerosis (MS), HMGB1 expression was found to be upregulated in brain active lesions from patients." (PMID 25879961, 2015). "A recent study demonstrated high serum levels of HMGB1 in patients with multiple sclerosis." (PMID 37511276, 2023). "We have recently determined that progenitor cells from multiple sclerosis patients exhibit a cellular senescent phenotype and release extracellular HMGB1 which directly impaired the maturation of oligodendrocyte progenitor cells (OPCs) to myelinating oligodendrocytes (OLs)." (PMID 35573828, 2022). "High mobility group box 1 protein (HMGB1) is known to be a trigger of inflammation in experimental autoimmune encephalomyelitis (EAE), an animal model of multiple sclerosis (MS)." (PMID 33868221, 2021). "In multiple sclerosis patients and experimental autoimmune encephalomyelitis models, the TLR4 was up-regulated and HMGB-1, a TLR4 ligand, plays a role in the disease progression." (PMID 30877182, 2019). "Multiple sclerosis is not the only instance where extracellular HMGB1 may negatively impact white matter." (PMID 35573828, 2022).
cerebral infarction (22 papers, 2011 to 2025). An ischemic condition of the brain, producing a persistent focal neurological deficit in the area of distribution of the cerebral arteries. "In this study, after confirming the protective effects of Gly in both rats and mice, we report for the first time that Gly reduces brain infarction by inhibiting T cell activity associated with HMGB1 release." (PMID 27609334, 2016). "HMGB1 plays a dual role after cerebral infarction by causing both damage and repair." (PMID 37062906, 2023). "HMGB1 plays a neurotrophic role in acute white matter stroke, whereas it causes sustained activation of inflammation and plays a damaging role in chronic white matter ischemia, indicating that it exhibits diverse functional roles in different cerebral infarction subtypes." (PMID 37062906, 2023). "In this review, we explain its effect on different subtypes of cerebral infarction and its key mechanism based on the spatiotemporal dynamics and modifications of HMGB1 after cerebral infarction." (PMID 37062906, 2023). "Animal experimental studies have demonstrated that both anti‐HMGB1 antibody and glycyrrhiza sweetener injections can reduce the infarction volume, indicating that HMGB1 released after cerebral infarction is mainly damaging." (PMID 37062906, 2023). "HMGB1 plays a complex role in cerebral infarction, which is related to not only the modification of HMGB1 and bound receptors but also different stages and subtypes of cerebral infarction." (PMID 37062906, 2023). "Among these mechanisms, the transfer of mononuclear macrophages from outside the brain to the infarct site after cerebral infarction by endocytosing HMGB1 is crucial, followed by lysosomal digestion." (PMID 37062906, 2023). "The authors also observed the overactivation of monocytes and depletion of mature monocytes by the HMGB1–RAGE pathway in the acute phase of cerebral infarction." (PMID 37062906, 2023). "future studies on HMGB1 should investigate the spatial and temporal dynamics of HMGB1 after cerebral infarction." (PMID 37062906, 2023). "In this reviews,we explained its effect on different subtypes of cerebral infarction and its key mechanism based on the Spatiotemporal dynamics and Modifications of HMGB1 after cerebral infarction." (PMID 37062906, 2023). "Studies have demonstrated the vital role of HMGB1 in the repair of neural tissues after cerebral infarction." (PMID 37062906, 2023). "Several studies have exhibited that the blood HMGB1 concentration after cerebral infarction is positively correlated with cerebral infarction severity and poor prognosis." (PMID 37062906, 2023). "The expression of ligands, such as HMGB1 and S100B, was much higher in the presence of cerebral infarction." (PMID 35725479, 2022). "A remarkable reduction in cerebral infarction was accomplished upon treatment with neutralizing anti-HMGB1 monoclonal antibody (mAb)." (PMID 32479555, 2020). "HMGB1 exaggerated brain infarction through the activation of inflammatory responses in the ischemic region." (PMID 32479555, 2020). "HMGB1 is also expressed in microglia, and the extent of cerebral infarct can be significantly reduced by the inhibition of microglial HMGB1 expression." (PMID 31001089, 2019). "In neuronal cells it has been reported that extracellular HMGB1 aggravates the tissue damage in ischemic brain infarction models." (PMID 22792152, 2012). "The inhibition of HMGB1 can be an effective strategy for treating cerebral infarction injury." (PMID 38740617, 2025). "Several studies have shown that glycyrrhizic acid and its hydrolyzed product glycyrrhetinic acid can reduce the size of cerebral infarction, restore motor function, inhibit M1 microglia activation, enhance M2 activation, and induce neural regeneration by inhibiting HMGB1." (PMID 38740617, 2025).
cerebral infarction (continued). "Our previous work demonstrated that neutralizing HMGB1 with a monoclonal antibody (mAb) significantly reduced brain infarction, hemorrhage, and traumatic brain injury in rat models, primarily by protecting the blood–brain barrier (BBB) and inhibiting the inflammatory cascade." (PMID 40943562, 2025). "(2020) reported that the elevated plasma HMGB1 levels in patients with cerebral infarction may be related to ONOO production." (PMID 37062906, 2023). "The present study describes the role of HMGB1 in the complex pathophysiological mechanism of cerebral infarction and specifically analyses the role of HMGB1 in cerebral infarction subtypes to provide novel insights into the precise treatment of cerebral infarction." (PMID 37062906, 2023). "Moreover, future studies on HMGB1 should attempt to integrate different stages and infarct subtypes of cerebral infarction." (PMID 37062906, 2023). "The functional roles of HMGB1 in cerebral infarction are poorly understood." (PMID 37062906, 2023). "Thus, future studies on HMGB1 should investigate the spatial and temporal dynamics of HMGB1 after cerebral infarction." (PMID 37062906, 2023). "The Hp‐HMGB1 complex has been reported to increase the number of M2 macrophages, and it is suggested that Hp achieves this via binding to HMGB1 and enhancing their repair function in cerebral infarction." (PMID 35243897, 2022). "In addition, HMGB1 knockdown mediated by siRNA, as well as HMGB1 inhibition mediated by HMGB1 A-box, significantly reduces cerebral infarction volume in the rat middle cerebral artery occlusion (MCAO) model." (PMID 33335763, 2020). "We conducted further animal experiments and found that HMGB1 inhibition could reduce brain edema and cerebral infarction area after HI." (PMID 31920543, 2019). "As HMGB1 induced microglial polarization to an M1 phenotype, leading to increased neurotoxicity, we then explored whether inhibition of HMGB1 could attenuate HI-induced brain damage using edema assessment and cerebral infarction detection." (PMID 31920543, 2019). "HMGB1 released after cerebral infarction is extensively involved in the pathological injury process in the early stage of cerebral infarction, whereas it is involved in the promotion of brain tissue repair and remodeling in the late stage of cerebral infarction." (PMID 37062906, 2023). "Thus, HMGB1 plays a complex role in cerebral infarction, which is related to not only the modification of HMGB1 and bound receptors but also different stages and subtypes of cerebral infarction." (PMID 37062906, 2023). "Calycosin significantly reduced neurological impairments and brain infarction in a dose-dependent manner, alleviated neuronal damage and decreased the expression of pyroptosis-related markers, including NLRP3, GSDMD, HMGB1, IL-1β, IL-18, and caspase-1." (PMID 40606597, 2025). "HMGB1 released from the activated astrocytes after cerebral infarction promotes EPC proliferation through RAGE, and HMGB1 facilitates EPC migratory aggregation toward the peri‐infarct cortex." (PMID 37062906, 2023). "In summary, our study determined that DPSCs‐Exos contributed to the inhibition of HMGB1/TLR4/MyD88/NF‐κB pathway and alleviated the cerebral I/R damage (including brain oedema, cerebral infarction and neurological deficit) in mice after tMCAO." (PMID 34231932, 2021). "We studied the expression of inflammation factors of RAGE, HMGB1, AGE, and S100B after cerebral infarction in rats treated with vx-765 to better understand the mechanism of RAGE in BBB damage." (PMID 33584203, 2020). "HMGB1/TLR‐4 signaling pathway activation promotes astrocyte‐induced MMP9 secretion, which may be one of the blood–brain barrier disruption mechanisms after cerebral infarction." (PMID 37062906, 2023). "Moreover, HMGB1 promotes macrophage activation through the RAGE, suggesting that HMGB1 also plays a vital role in the activation of the adaptive immune system after cerebral infarction." (PMID 37062906, 2023).
cerebral infarction (continued). "However, the role of HMGB1 in other neuronal death pathways after cerebral infarction has not been reported yet." (PMID 37062906, 2023). "However, reduced‐HMGB1 exerts no considerable effect on these inflammatory mediators, suggesting that HMGB1 may not be a key mediator of intracranial inflammation in the ultra‐early phase of cerebral infarction." (PMID 37062906, 2023). "However, clearance of HMGB1 released after cerebral infarction may be partially dependent on the involvement of MSR1 or MARCO, and further studies are warranted to understand the mechanism of removal of HMGB1 released after cerebral infarction." (PMID 37062906, 2023).
influenza (22 papers, 2011 to 2025). An acute viral infection of the respiratory tract, occurring in isolated cases, in epidemics, or in pandemics; it is caused by serologically different strains of viruses (influenzaviruses) designated A, B, and C, has a 3-day incubation period, and usually lasts for 3 to 10 days. "Furthermore, the HMGB1-encoding plasmid also demonstrated adjuvant-like effects in the DNA-based influenza vaccine approach." (PMID 34960608, 2021). "Similar to that observed in the HIV vaccination, vaccination with plasmids encoding influenza antigen and HMGB1 can induce DC maturation by upregulating CD83, CD86, and CCR7, and mounted stronger neutralizing antibody response antigen-specific CD4+ and CD8+ T cells." (PMID 34960608, 2021). "Our data showing a lag of 2–4 days for induction of circulating HMGB1 in response to influenza, coupled with the partial efficacy of Eritoran as late as 6 days p.i., suggests there is a therapeutic window in influenza-induced ALI." (PMID 39699172, 2025). "In CR infected with human influenza strains, disease severity based on lung pathology and cytokine production correlated with serum HMGB1 levels, and were reduced by Eritoran treatment." (PMID 39699172, 2025). "The most important pathway involving proteins differentially expressed between patients with influenza and patients with bacterial infections was HMGB1/TLR signalling pathway." (PMID 35264246, 2022). "Therapeutic administration of Eritoran during influenza infection inhibited HMGB1 release in mice and cotton rats." (PMID 34282358, 2021). "Improved survival combined with significantly attenuated histological changes and neutrophil infiltration in the lungs of influenza- inoculated mice have been reported, despite that the treatment was based on xenogenic polyclonal antibodies against HMGB1." (PMID 32380958, 2020). "Previous studies have suggested that HMGB1 interacts with viral proteins to participate in the course of infection by viruses such as influenza and Borna disease." (PMID 29316268, 2018). "FP7 administration also strongly reduced cytokine mRNA and protein production and HMGB1 levels induced by influenza infection." (PMID 28106157, 2017). "In this model, influenza infection induces a cytokine storm and the accumulation of oxidized products of phospholipids in infected lungs or circulating HMGB1, both of which are inhibited by Eritoran therapy." (PMID 28106157, 2017). "Of the mice inoculated with 100 pfu (1 MLD50) influenza H1N1 virus and treated with anti-HMGB1 mAb (2 mg/kg, intravenously), 93.3 % were protected from influenza-induced death, whereas 53.3 % of infected mice administered control mAb died." (PMID 26067826, 2015). "Several researchers have already investigated HMGB1 and influenza and suggested the anti-influenza effects of different inhibitory agents of HMGB1, including ethyl pyruvate and some Chinese herbs." (PMID 26067826, 2015). "3-deoxysappanchalcone (3-DSC), a compound derived from Biancaea sappan (L.)Tod., has demonstrated anti-influenza and anti-allergic effects, though its role in HMGB1-mediated severe vascular inflammation remains unclear." (PMID 40430548, 2025). "Thus, therapies that block HMGB1 release or action, such as Eritoran or P5779, should be considered universal, adjunctive therapies to influenza vaccines." (PMID 29535197, 2018). "HMGB1 was first implicated in endotoxicity and Gram-negative sepsis and was shown to be released during severe murine influenza infection." (PMID 29535197, 2018). "Notably, recent studies have indicated that HMGB1 is an effective immune adjuvant molecule which enhances the humoral immune response of influenza and HIV in DNA vaccination." (PMID 29137362, 2017). "Therefore, FP7 can antagonize TLR4 activation in vitro and protect mice from severe influenza infection, most likely by reducing TLR4-dependent cytokine storm mediated by damage-associated molecular patterns (DAMPs) like HMGB1." (PMID 28106157, 2017).
influenza (continued). "After HMGB1 was first shown to have an additional function as a late mediator of endotoxin lethality, it has since been revealed as a protein with inflammatory cytokine activity in the pathogenesis of influenza, as well as in many other inflammatory diseases." (PMID 26067826, 2015). "Taken collectively, the host-derived DAMPs, HMGB1 and GRP, play important roles in mediating influenza-induced disease." (PMID 34282358, 2021). "Successful preclinical treatment results using specific HMGB1-, TLR4- or RAGE-antagonists further support that the HMGB1/RAGE/TLR4-axis is central in the pathogenesis of influenza infections." (PMID 32380958, 2020). "Recent studies suggest that influenza-induced lethality and ALI are due to the TLR4-stimulating effects of DAMPs such as OxPAPC and HMGB1, which are both TLR4 agonists." (PMID 28106157, 2017). "We found that in H1N1-inoculated mice, anti-HMGB1 mAb significantly suppressed the local production of IL-6 and TNF-α, key cytokines orchestrating the pathophysiology of highly virulent influenza strains." (PMID 26067826, 2015). "It has been demonstrated in preclinical and clinical studies that severe respiratory infections including influenza and human respiratory syncytial virus (HRSV) generate substantial extracellular HMGB1 release in pulmonary inflammation and that HMGB1-specific antagonists ameliorate these conditions." (PMID 32380958, 2020).